LYPLA1 (lysophospholipase 1)
Description:
Acts as an acyl-protein thioesterase. Hydrolyzes fatty acids from S-acylated cysteine residues in proteins such as trimeric G alpha proteins or HRAS. Acts as a palmitoyl thioesterase that catalyzes depalmitoylation of proteins, such as ADRB2, KCNMA1 and SQSTM1. Acts as a negative regulator of autophagy by mediating palmitoylation of SQSTM1, decreasing affinity between SQSTM1 and ATG8 proteins and recruitment of ubiquitinated cargo proteins to autophagosomes. Acts as a lysophospholipase and hydrolyzes lysophosphatidylcholine (lyso-PC). Also hydrolyzes lysophosphatidylethanolamine (lyso-PE), lysophosphatidylinositol (lyso-PI) and lysophosphatidylserine (lyso-PS) (By similarity). Has much higher thioesterase activity than lysophospholipase activity. Contributes to the production of lysophosphatidic acid (LPA) during blood coagulation by recognizing and cleaving plasma phospholipids to generate lysophospholipids which in turn act as substrates for ENPP2 to produce LPA.
Synonyms: APT-1; hAPT1; LPL-I; APT1; LPL1
Tractability: Small molecule: a structure with a bound ligand is known; a high-quality ligand is known. Antibody: UniProt places it where antibodies can reach, with high confidence; its Gene Ontology location is reachable by antibodies, with high confidence. PROTAC: ubiquitination databases record sites on it; its protein half-life has been measured; a small molecule that binds it is known.
Target class: Enzyme; Hydrolase
Chemical probes: ML-211, ML348, ML378, PALMOSTATIN B
Gene: Protein-coding gene on chromosome 8 (54,046,367 to 54,102,017, reverse strand). Ensembl gene ENSG00000120992.
Subcellular location: Cytoplasm; Cell membrane; Nucleus membrane; Endoplasmic reticulum
Subcellular location (Human Protein Atlas): Cytosol; Nucleoplasm
Pathways (Reactome):
Metabolism: eNOS activation
Signal Transduction: RAS processing
Gene Ontology:
Molecular function: lipase activity; palmitoyl-(protein) hydrolase activity; phosphatidylcholine lysophospholipase activity; phospholipase activity; protein binding; hydrolase activity
Biological process: fatty acid transport; negative regulation of aggrephagy; protein depalmitoylation; negative regulation of Golgi to plasma membrane protein transport
Cellular component: cytoplasm; cytosol; endoplasmic reticulum; extracellular exosome; mitochondrion; nuclear membrane; plasma membrane
Genetic constraint (gnomAD): Loss-of-function variants: 8 observed, 9.11 expected, observed/expected ratio (o/e) 0.88, 90% interval 0.51 to 1.56. That is too few expected variants to judge how well the gene tolerates losing a copy. Missense variants: 113 observed, 145.36 expected, observed/expected ratio (o/e) 0.78, 90% interval 0.67 to 0.91. Synonymous variants: 53 observed, 51.61 expected, observed/expected ratio (o/e) 1.03, 90% interval 0.82 to 1.29.
Homologues: Orthologues: macaque LYPLA1 (99% identical), rabbit LYPLA1 (94% identical), rat Lypla1 (92% identical), mouse Lypla1 (92% identical), pig LYPLA1 (80% identical), tropical clawed frog lypla1 (80% identical), zebrafish lypla1 (78% identical), guinea pig LYPLA1 (74% identical), Drosophila melanogaster Apt1 (51% identical), Caenorhabditis elegans ath-1 (50% identical). Paralogues in human: LYPLA2 (68% identical), LYPLAL1 (33% identical).
Diseases named in the same sentence as LYPLA1 in open-access papers:
LYPLA1 is named in the same sentence as 28 diseases in open-access papers, as found by Europe PMC text mining. Sharing a sentence is not in itself a finding about the gene and the disease. The quoted sentences say what the papers report.
diabetes (4 papers, 2013 to 2025). "Thus, based on our manual inspection of the metabolomics-proteomics data and in line with the evidence, we suggest that simulated diabetes evokes inflammation on BCAEC and that PAFAH1B2 and LYPLA1 play a role in modulating such process." (PMID 35835939, 2022).
breast carcinoma (3 papers, 2023 to 2025). "The expression of DGAT1, DUT, LYPLA1, and POLR2K was linked to an increased risk of breast cancer, whereas SMPD4 was associated with a protective effect." (PMID 37644433, 2023). "LYPLA1 was found to be associated with poor prognosis in lung adenocarcinoma, while POLR2K was identified as one of the top 10 cancer immunotherapy proteins related to breast cancer by machine-learning predictions." (PMID 37644433, 2023).
cervical cancer (3 papers, 2023 to 2025). A primary or metastatic malignant neoplasm involving the cervix. "Additionally, LYPLA1 was found to be highly expressed in malignant cervical cancer tissues, where it was associated with the upregulation of EMT-inducing TIAM1 and GREM1 and a decrease in mesenchymal markers." (PMID 37644433, 2023).
non-small cell lung carcinoma (3 papers, 2020 to 2022). A group of at least three distinct histological types of lung cancer, including non-small cell squamous cell carcinoma, adenocarcinoma, and large cell carcinoma. "LYPLA1 acting as a homodimer, exhibits both depalmitoylating as well as lysophospholipase activity, plays a tumor-promotor role in non-small cell lung cancer cells." (PMID 33352742, 2020). "This is consistent with previous in vitro experimental data, reporting on a LYPLA1 dependent proliferation and migration of non-small cell lung cancer cells in 2D cultures." (PMID 32733643, 2020).
glioma (2 papers, 2020 to 2023). A benign or malignant brain and spinal cord tumor that arises from glial cells (astrocytes, oligodendrocytes, ependymal cells). "Each glioma patient was assigned a risk score according to the following formula: risk score = (0.2433)*RAB13 + (0.4201)*LYPLA1 + (0.0013)*GAS1 + (−0.0463)*VAMP2 + (0.5165)*CNIH4 + (0.3109)*PICK1 + (−0.0864)*RAB6B + (0.0978)*GOLT1." (PMID 37062068, 2023). "In addition, two distinct mSHs, namely lysophospholipases A1 and A2 (LYPLA1/2 ~ 25 kDa) showed prominent, yet comparable activity in control brain and glioma." (PMID 32190011, 2020).
Huntington disease (2 papers, 2021 to 2024). Huntington disease (HD) is a rare neurodegenerative disorder of the central nervous system characterized by unwanted choreatic movements, behavioral and psychiatric disturbances and dementia. "We confirmed the association of endogenous UBL3 with the RNA-binding proteins FUS and HPRT1—both listed in the Neurodegenerative Diseases Variation Database (NDDVD)—and with LYPLA1, which is involved in Huntington’s disease, using immunoprecipitation (IP)-western blotting analysis." (PMID 39148092, 2024).
atherosclerosis (1 paper, 2021). A disease characterized by the build-up of fatty material and calcium deposition in the arterial wall resulting in partial or complete occlusion of the arterial lumen. "In rat atherosclerosis PCR array, Abca1, Bax, Bcl2, Bcl2a1, Cd44, Fabp3, Hbegf, Lypla1, Ptgs1, Selplg, Tgfb2, Tnc, and Vegfa had reverse trend between WT and MU groups, while the trends of Bcl2l1, Bid, Birc3, Cxcl1, Fas, Fn1, Itga2, Itga5, Lif, Nfkb1, Nr1h3, Ppard, and Sod1 were consistent." (PMID 34545275, 2021).
invasive breast carcinoma (1 paper, 2018). A carcinoma that infiltrates the breast parenchyma. "The APT1 gene, LYPLA1, is amplified across a wide variety of tumor types, including 31.8%, 23.2% and 13.8%, in neuroendocrine prostate cancer, uterine carcinosarcoma and invasive breast carcinoma, respectively." (PMID 29648538, 2018).
tumor (20 papers, 2008 to 2025). "Seeking an immunohistochemistry-compatible target we, therefore, assumed that lysophospholipid depletion in the tumor area of the HNSCC image may be associated with an increase in the expression of the lysophospholipid degrading enzyme lysophospholipid lipase A1 (LYPLA1)." (PMID 32733643, 2020). "LYPLA1 was found to play a tumor-promoting role in non-small cell lung cancer (NSCLC) cells in vitro, with suppression of its expression leading to significant inhibition of proliferation, migration, and invasion of NSCLC cells." (PMID 37644433, 2023). "Selected regions of the neoplastic and healthy tissue areas were subjected to histopathological scoring for determining LYPLA1 expression in the tumor, tumor and healthy stroma as well as in the healthy epithelium." (PMID 32733643, 2020). "Displaying expression levels in the tumor vs. in the healthy stroma revealed a clear accumulation of LYPLA1 in the tumor for most cases, largely consistent with MS image results for LPC[16:0] and LPC[18:2]." (PMID 32733643, 2020). "Further we show that the lysophospholipid digesting LYPLA1 is accumulated in the tumor region of HNSCC tumors." (PMID 32733643, 2020). "Altogether, expression and distribution of LPC[16:0], LPC[18:2] and LYPLA1 appeared to inversely correlate, supporting a lipid-based diagnosis of the tumor." (PMID 32733643, 2020). "We optionally performed the analysis adjusted for variability in tumor cell percentage across the tumor cuts (range: 60–100%) and noted lipases, notably, Acyl-protein thioesterase 1 (LYPLA1) and Fatty-acid amide hydrolase 2 (FAAH2), that manifested significant dysregulations across LUAD subtypes." (PMID 40425563, 2025). "has found LPC-digested lysophospholipase 1 (Human Acyl-protein thioesterase 1, LYPLA1) accumulation in the tumor region, suggesting that the progression of HNSCC in vivo may depend on lysophospholipid (LP) supply." (PMID 37519782, 2023). "Finally, LYPLA1 expression was found higher in most tumor cases examined as compared to their healthy epithelium counterparts as well." (PMID 32733643, 2020). "Furthermore, marker potential of lysophospholipids was supported by elevated expression levels of the lysophospholipid degrading enzyme lysophospholipase A1 (LYPLA1) in the tumor regions of paraffin-embedded HNSCC samples." (PMID 32733643, 2020). "In addition, LYPLA1 expression was found higher in most tumor cases examined as compared to their tumor stroma counterparts, which was in good agreement with LPC[16:0] and LPC[18:2] distribution in the MS image." (PMID 32733643, 2020). "The upregulation of 24 palmitoylation regulating genes in tumor tissues (e.g., ZDHHC12, LYPLA1) compared to normal tissues suggests a tumor-promoting role for palmitoylation in LGG." (PMID 40535771, 2025). "In locales of elevated tumor cell density, surfeit locus protein 4 (SURF4) and the lipid metabolic gene lysophospholipase I (LYPLA1) have been corroborated as biomarkers inversely related to favorable outcomes." (PMID 39439806, 2024).
cancer (10 papers, 2016 to 2025). A tumor composed of atypical neoplastic, often pleomorphic cells that invade other tissues. "LOXL1-AS1 depletion suppresses proliferation, migration, invasion, and angiogenesis of this type of cancer cells through downregulating Lysophospholipase 1 (LYPLA1), a direct target of miR-526b-5p." (PMID 39136001, 2024).
infection (3 papers, 2016 to 2021). The state of being infected such as from the introduction of a foreign agent such as serum, vaccine, antigenic substance or organism. "The LYPLA1 gene from Ovis aries cloned in this study may take apart in the immune response of the host towards the infection of bacteria." (PMID 27483239, 2016). "However, there is no investigation about the relationship between LYPLA1 and infection of bacteria." (PMID 27483239, 2016).
bacterial infection (1 paper, 2016). "There are hardly any studies about the relationship between the expression profile of LYPLA1 and bacterial infection." (PMID 27483239, 2016). "However, the expression profiles of LYPLA1 gene of the host infected with bacteria and whether LYPLA1 takes part in the host immune response after the bacterial infection had not been investigated before." (PMID 27483239, 2016).
LYPLA1 also shares sentences with these, for which no sentence is quoted: pancreatic cancer (3 papers); Arthritis (2); septic arthritis (2); synovitis (2); abscess (1); endothelial dysfunction (1); follicular carcinomas (1); hyperthyroidism (1); lung adenocarcinoma (1); melanoma (1); metastatic tumors (1); ovarian serous cystadenocarcinoma (1); papillary carcinoma (1); skin abscesses (1); thyroid papillary carcinomas (1); uveal melanoma (1).